NLRC5 (NLR family CARD domain containing 5)
Diseases named in the same sentence as NLRC5 in open-access papers (continued):
Sharing a sentence is not in itself a finding about the gene and the disease.
tumor (continued). "All cases presented staining for NLRC5, Beclin 1 and LC3 were predominantly detected in the cytoplasm of tumor cells." (PMID 38961101, 2024). "Even though MHC-I expression induced by NLRC5-SA in B16 cells was discernibly lower than NLRC5-FL-mediated MHC-I induction, NLRC5-SA expression significantly reduced B16 tumor growth as strongly as NLRC5-FL did." (PMID 37108368, 2023). "Our findings show that both NLRC5 constructs upregulate MHC-I in murine and human cancer cells, promote tumor growth control and induce profound modifications of MAPs that display a partial overlap." (PMID 37108368, 2023). "As MHC class I genes are important to present tumor neo-antigen to CD8+ T cells, it implies a tumor-suppressing function of NLRC5." (PMID 34307322, 2021). "We show that several genes aberrantly expressed in FP tumors have known tumor promoting biology in humans, including CTHRC1 and NLRC5, and provide support that disruption of the Wnt signaling pathway is a feature of FP." (PMID 33717164, 2021). "Studies have shown that NLRC5 is a transcriptional regulator of MHC class I genes and through this, activates cytotoxic CD8+ T cells as part of an anti-tumor immune response." (PMID 33717164, 2021). "NLRC5 can be used not only to restore MHC-I expression and tumor immunogenicity but also to discover cancer antigenic peptides and to predict unresponsiveness to cancer immunotherapy." (PMID 33671123, 2021). "We showed that stable expression of NLRC5 in B16 cells induces MHC-I and APM genes, upregulates cell surface MHC-I expression and promotes the processing and presentation of an endogenous tumor antigenic peptide from PMEL-1 (gp100) protein." (PMID 33671123, 2021). "Here, by sequencing of 172 FL tumours, we found the MHC‐I transactivator NLRC5 was the most frequent gene abnormality in the MHC‐I pathway." (PMID 35845006, 2020). "NLRC5 is famous as a transactivator of MHC class I and also plays a central role in tumor immune escape through regulation of MHC class I." (PMID 31824312, 2019). "NLRC5, a member of the NOD-like receptor gene family and widely expressed in tumor tissues, is a key transcriptional regulator of MHC class I molecules." (PMID 29394898, 2018). "In human keloid, a fibrotic tumor, characterized by extensive ECM deposition and hyperproliferation of fibroblasts in the skin, NLRC5 is also highly expressed." (PMID 28261210, 2017). "The functionality of NK cells from Nlrc5−/− and CD4cre Nlrc5fl/fl mice was then assessed by testing the ability to reject B2m−/− splenocytes or MHCI-negative RMA-S tumour cells." (PMID 26861112, 2016). "The dedicated activity of NLRC5 to transactivate MHC class I and APM genes renders this NLR particularly interesting to study in the context of tumor development, immunity, and escape." (PMID 27437103, 2016). "NLRC5, a key regulator of MHC-I antigen presentation, exhibits context-dependent roles in tumor immunity; however, its function in ESCC remains unclear." (PMID 41976340, 2026). "Consequently, NLRC5 contributes to reconstituting the expression and antigen presentation of B2M/MHC-I on tumor cells to potentiate CD8+ T cell dominated anticancer immunity." (PMID 40191187, 2025). "In contrast, epigenetic silencing of key transcriptional regulators such as NLRC5 (for MHC‐I) and CIITA (for MHC‐II) appears more common across a broader range of tumours and may be pharmacologically reversible." (PMID 40673641, 2025). "To validate the impact of NLRC5 on HCC patient survival, we first performed prognostic analysis of NLRC5 in HCC tumor tissues and adjacent non-tumor tissues through the database." (PMID 39132868, 2024). "We show that tumor cells have an increased expression of several markers (CD47, IL7R, NKG7, CD80, CD84, CSF1R, NLRC5/CITA, CD2 and IRF3) that may be involved in regulating the level of immune infiltration and the effect on tumor immunity." (PMID 39001353, 2024).
tumor (continued). "As the clinical application of NLRC5 is constrained by its large size, we examined whether a smaller NLRC5-CIITA fusion protein, dubbed NLRC5-superactivator (NLRC5-SA) as it retains the ability to induce MHC-I, could be used for tumor growth control." (PMID 37108368, 2023). "PRMT5 regulates antigen presentation by controlling NLRC5 expression, which regulates the expression of MHC class I genes, and the inhibition of PRMT5 expression leads to the increased expression of surface MHC class I and tumor cell recognition." (PMID 38136558, 2023). "Recent evidence has indicated that tumors could be more responsive to ICIs when expressing NLRC5 and APM proteins in the tumor niche." (PMID 38235131, 2023). "NLRC5 is a key regulator of MHC class I expression and CD8+ T cell responses 45, 46, where the reduced expression in cancers correlates with decreased anti-tumor cytotoxicity." (PMID 36632221, 2023). "IFN-γ is mainly produced by T and NK cells It can induce a positive feedback in the STAT1 pathway that triggers the expression and activation of STAT1 and other downstream genes, such as NLRC5, CIITA, and TAP1, and increases the immune response in the tumor microenvironment." (PMID 34220868, 2021). "PCR based evaluation of NLRC5 gene expression in tumor biopsies would not be appropriate as NLRC5 is highly expressed in hematopoietic cells that infiltrate tumors." (PMID 33671123, 2021). "Interestingly, the absence of caspase-1 activity in tumor cells was not only associated with decreased mRNA levels of caspase-1 and downstream cytokines IL-18 and IFNγ, but also with upstream inflammasome sensors or regulators, among which NLRC5 is of particular interest." (PMID 33430344, 2021). "The frequency of the genetic aberration type varied considerably by tumour type; however, irrespective of the genetic mechanism, NLRC5 gene expression was reduced and low expression was consistently significantly associated with inferior patient survival." (PMID 35845006, 2020). "According to these observations, the regulation of MHC class I expression on tumor cells by Fhit is not mediated by NLRC5 gene expression." (PMID 32545680, 2020). "Basic experiments research suggested that silencing NLRC5 could subsequently inhibit HCC cells proliferation, migration, invasion, and tumor formation." (PMID 31824312, 2019). "Conversely a lower NLRC5 expression has been reported to influence the MHC class I expression leading to an impaired ability to elicit CD8+ T-cell activation, which represent a way used by the tumor cells to escape the host immune system." (PMID 29408916, 2018). "Surprisingly, these results are opposing the established negative correlation of NLRC5 expression and tumor immunogenicity mediated by MHC class I-dependent antigen presentation and CTL-mediated restriction of malignant cells [reviewed in Ref." (PMID 28261210, 2017). "Additionally, tumor cells in these regions upregulated genes such as IL7R, CD80, and NLRC5, which are involved in T cell survival, co-stimulatory signaling, and antigen presentation, thereby supporting T cell recruitment, activation, and sustained immune responses." (PMID 41001043, 2025). "In addition to immune regulation, NLRC5 may also involve in the regulation of HCC malignant phenotype, which contributes to tumor progression." (PMID 39132868, 2024). "Thus, NLRC5-SA can be used to overcome the size constraint of full-length NLRC5 for delivery to MHC-I defective tumors via viral vectors to induce tumor immunogenicity and to identify tumor antigenic peptides for immunotherapy applications." (PMID 37108368, 2023).
tumor (continued). "For example, NLRC5-deficient cells could not effectively elicit CD8+ T-cell activation, along with diminished cytolytic activity to tumor cells." (PMID 34307322, 2021). "Finally, we observed a novel mechanism of transcriptional regulation of MHC-I expression on tumor cells by expression of the MHC-I transactivator NLRC5 (NOD-like receptor C5) and found that expression of NLRC5 by cancer cells enhanced cytotoxic cytokine production by CD8+ T cells." (PMID 32355214, 2020). "Genes of the antigen-processing machinery and regulation (IRF1, IRF2, NF-κB1, NF-κB2, NLRC5, TAP1, TAP2, TAPBP) were not significantly expressed throughout all of the analyzed tumor transcriptomes." (PMID 35892842, 2022). "Importantly, P4 treatment induced NLRC5 and BTN3A1 co-expression in tumor tissue in our mice experiments compared to those without P4 treatment." (PMID 36632221, 2023). "NLRC5 not only transactivates classical MHC-Ia genes but also induces non-classical MHC-Ib genes, which may impact tumor immune surveillance." (PMID 33671123, 2021).
cancer (57 papers, 2015 to 2025). A tumor composed of atypical neoplastic, often pleomorphic cells that invade other tissues. "Inhibition on the miR-4319, therefore, facilitates expressional promotion on NLRC5 to repair deficient expression of MHC class I on cancer cells." (PMID 40596738, 2025). "MHC-I deficiency in cancers is commonly caused mostly by NLRC5 loss, which has been regarded as poor prognosis for many cancers." (PMID 37508545, 2023). "TCGA data from diverse cancers revealed that loss of NLRC5 expression is the most common defect among MHC-I-related genes and correlates with reduced CTL infiltration and poor patient survival." (PMID 37108368, 2023). "NLRC5 is a transcriptional activator that localizes to conserved S/X/Y regions within the promoters of class I pathway genes, and NLRC5 copy number loss is a common alteration across many cancers." (PMID 35775490, 2022). "Genetic alterations, copy number loss, and somatic mutations of NLRC5 results in reduced MHC-I expression in various cancer types." (PMID 35296095, 2022). "Studies on NLRC5 deficient mice and single cell RNAseq data from human cancers my shed light on this issue." (PMID 33671123, 2021). "A few studies have reported elevated NLRC5 protein expression in certain cancers that is associated with poor survival." (PMID 33671123, 2021). "In human cancers, genetic and epigenetic changes in NLRC5 gene are associated with impaired expression of MHC class I and related genes and reduced activity of CD8+ cytotoxic T cells." (PMID 33547395, 2021). "Is the predictive potential of NLRC5 influenced by the mutational load and the frequency of neoantigen generation of different cancers?" (PMID 33671123, 2021). "Subsequent reports that the expression of NLRC5 is widely compromised in many cancers by deletions, mutations and epigenetic repression highlighted the possibility of exploiting NLRC5 to reverse MHC-I expression defects in cancers." (PMID 33671123, 2021). "This idea gained traction with the findings that the loss of NLRC5 expression resulting from genetic and epigenetic causes is the most common mechanisms of MHC-I deficiency in cancers, and that loss of NLRC5 has poor prognosis for many cancers." (PMID 33671123, 2021). "Overexpression of NLRC5 in cancer cells dramatically changed their immunogenicity, associated with upregulation of critical antigen processing and presentation components, and improving their recognition by specific T cells." (PMID 32355214, 2020). "Whilst for the NF-κB pathway, CYLD and TRAF3 mutations appear to occur at a similar high rate in both cancers (8–11% rates), followed by the same rate of mutations of NLRC5 (6% rates)." (PMID 29933636, 2018). "Analogous to CIITA for MHCII, NLRC5/CITA has been shown to be a key regulator of MHCI expression that has been implicated in cancer." (PMID 27729860, 2016). "High expression of NLRC5 has been associated with favorable prognosis in many types of cancer." (PMID 39132868, 2024). "Conversely, we found that cancers with NLRC5 gain were more likely to undergo CPB/EP300 loss." (PMID 33602823, 2021). "In fact, identification of NLRC5 deficient cancers would also make it possible to identify patients who are likely to benefit from therapeutic restoration of NLRC5 (discussed in an earlier section) that can boost the effectiveness of ICI therapy and generate lasting antitumor immunity." (PMID 33671123, 2021). "The possibility that the antitumor versus pro-tumorigenic roles of NLRC5 may be influenced by the mutational load and the frequency of neoantigen generation of different cancers also need to be considered." (PMID 33671123, 2021). "Therefore, investigations into the role of NLRC5 expression and mutation load for the prediction of treatment outcomes in these cancers is of interest." (PMID 33547395, 2021).
cancer (continued). "Hypermethylation of the NLRC5 gene promoter was reported to be the most common epigenetic mechanism associated with reduced MHC-I expression in human cancers and cell lines that could be reversed by 5-Aza treatment." (PMID 33671123, 2021). "Furthermore, novel studies reveal that NLRC5 is up-regulated and implicated in tumorigenesis by promoting cell proliferation, migration, and invasion in high inflammatory state related cancer." (PMID 33013364, 2020). "Thus, it is feasible that NLRC5 expression / mutation load might also be useful for predicting outcomes of other cancer patients treated with anti-PD-1/PD-L1 antibody therapy." (PMID 33547395, 2021). "As ablation of the Nlrc5 gene does not completely abolish MHC-I expression, especially in non-hematopoietic cells, it should be possible to test using NLRC5-deficient mice whether NLRC5 plays a crucial role in cancer immune surveillance and selection of immune escape variants." (PMID 33671123, 2021). "Thus, loss of NLRC5 represents a potential mechanism of immune evasion in cancer cells." (PMID 32355214, 2020). "In cancer immunotherapy and the fight against cancer immune evasion, NLRC5 promotion in conjunction with MHC-I augmentation is essential." (PMID 40098955, 2025). "NLRC5 plays a pivotal role in cancer immunosurveillance by transactivating MHC-I, which is typically HLA-ABC in humans." (PMID 40098955, 2025). "The results showed that the activation of NF-κB can reverse the effect of NLRC5 on the dMMR status of EC and inhibit the proliferation, migration, and invasion of cancer cells." (PMID 38822039, 2024). "Lastly, NLRC5/CITA induces the expression of genes encoding critical components of the MHC class I pathway, which is essential for the cancer antigen presentation and recruitment/activation of cytotoxic T cells." (PMID 39001353, 2024). "A thorough investigation of links between autophagy, IFNγ, and CITA/NLRC5 is necessary to further elucidate the complex interactions between autophagy and antigen presentation in cancer." (PMID 39409895, 2024). "The results showed that high expression of NLRC5 is a risk factor associated with poor prognosis in HCC patients, which differs from the performance of NLRC5 in other cancers." (PMID 39132868, 2024). "Nevertheless, the inconsistent role of NLRC5 in different microenvironment of cancer, such as in EC, need to be investigated." (PMID 38822039, 2024). "Statistical analysis based on the H-score estimated in IHC staining revealed a significant difference in NLRC5 expression between the CC tissues and para-cancer tissues (z = 4.796, p < 0.01)." (PMID 38961101, 2024). "In the present study, we compared the impact of NLRC5-FL and NLRC5-SA on MAPs towards exploiting NLRC5 for the discovery of cancer antigenic peptides." (PMID 37108368, 2023). "In general, genetic and epigenetic alteration-caused loss of NLRC5 paves the way for MHC-I deficiency, which is a common mechanism of cancer unresponsiveness to immunotherapy." (PMID 37508545, 2023). "NLRC5 has been suggested as a form of cancer immunotherapy that complements effective immune checkpoint inhibitor treatment." (PMID 36632221, 2023). "This increase was greater with NLRC5-SA in the human cancer cell lines A549 and T47D, similar to earlier findings on HEK293T cells." (PMID 37108368, 2023). "We show that stable NLRC5-SA expression in mouse and human cancer cells upregulates MHC-I expression." (PMID 37108368, 2023). "Next, we examined the effect of NLRC5-SA in human cancer cell lines selected from the NCI-60 cell line panel based on low basal expression of NLRC5 and HLA genes." (PMID 37108368, 2023). "Subsequently, they also reported in the following studies that NLRC5 expression was lost in varying cancers and the loss was correlated with the loss of CTL activation in several types of cancer." (PMID 37508545, 2023).